AMTN (amelotin)
Description:
Is a promoter of calcium phosphate mineralization, playing a critical role in the formation of the compact, mineralized, aprismatic enamel surface layer during the maturation stage of amelogenesis.
Synonyms: UNQ689; RSTI689; AI3B
Tractability: Antibody: UniProt places it where antibodies can reach, with medium confidence; UniProt predicts a signal peptide or a membrane-spanning region; its Gene Ontology location is reachable by antibodies, with medium confidence.
Gene: Protein-coding gene on chromosome 4 (70,518,569 to 70,532,743, forward strand). Ensembl gene ENSG00000187689.
Subcellular location: Secreted
Pathways (Reactome):
Metabolism of proteins: Post-translational protein phosphorylation; Regulation of Insulin-like Growth Factor (IGF) transport and uptake by Insulin-like Growth Factor Binding Proteins (IGFBPs)
Gene Ontology:
Molecular function: protein binding
Biological process: positive regulation of biomineral tissue development; odontogenesis of dentin-containing tooth; positive regulation of enamel mineralization
Cellular component: basement membrane; cell-cell junction; endoplasmic reticulum lumen; extracellular matrix; extracellular region
Genetic constraint (gnomAD): Loss-of-function variants: 24 observed, 20.26 expected, observed/expected ratio (o/e) 1.18, 90% interval 0.86 to 1.66. The upper end of that interval is the gene's LOEUF score, 1.66, which puts it in group 6 of 6, group 1 being the genes least tolerant of losing a copy. Missense variants: 217 observed, 230.23 expected, observed/expected ratio (o/e) 0.94, 90% interval 0.84 to 1.05. Synonymous variants: 76 observed, 92.44 expected, observed/expected ratio (o/e) 0.82, 90% interval 0.68 to 1.
Homologues: Orthologues: chimpanzee AMTN (98% identical), macaque AMTN (92% identical), pig AMTN (72% identical), dog AMTN (70% identical), rabbit AMTN (67% identical), rat Amtn (61% identical), guinea pig AMTN (60% identical), mouse Amtn (60% identical).
Diseases named in the same sentence as AMTN in open-access papers:
AMTN is named in the same sentence as 10 diseases in open-access papers, as found by Europe PMC text mining. Sharing a sentence is not in itself a finding about the gene and the disease. The quoted sentences say what the papers report.
ameloblastoma (3 papers, 2017 to 2025). The most common odontogenic tumor, arising from the epithelial component of the embryonic tooth and usually affecting the molar-ramus region of the mandible or maxilla. "We also found that gene expression of amelotin (AMTN), which encodes a secreted protein specifically expressed during the late stages of enamel formation, greatly increased in five out of seven ameloblastoma tumors compared to normal tissues." (PMID 32096304, 2020). "Although the relationship between AMTN overexpression and development of ameloblastoma is still unknown, our finding might provide novel insight into the molecular pathogenesis of ameloblastoma for future research." (PMID 32096304, 2020).
periodontitis (2 papers, 2018 to 2019). An acute or chronic inflammatory process that affects the tissues that surround and support the teeth. "Therefore, the regulation of AMTN gene transcription by IL‐1β in gingival epithelial cells is a crucial topic for onset and progression of periodontitis." (PMID 29928577, 2018). "We have previously reported that AMTN was highly induced in inflamed gingiva obtained from patients with chronic periodontitis 25, 26, and the results in this study have proven that the AMTN gene transcription was upregulated by inflammatory cytokine in gingival epithelial cells." (PMID 29928577, 2018).
Alzheimer disease (1 paper, 2021). A progressive, neurodegenerative disease characterized by loss of function and death of nerve cells in several areas of the brain leading to loss of cognitive function such as memory and language. "Eleven of those follow an autosomal-dominant inheritance pattern and span a wide range of phenotypes, including three genes linked to various dental issues (AMTN, ENAM, DSPP) and APP known to cause Alzheimer disease when duplicated." (PMID 33315133, 2021).
breast carcinoma (1 paper, 2022). "Amtn (amelotin) may play a role in the controlled mineralization of hydroxyapatite that is an early diagnostic marker for breast cancer, is involved in enhancing breast cancer progression, and is associated with poor breast cancer prognosis." (PMID 35768767, 2022).
dental fluorosis (1 paper, 2014). A condition that results from excessive fluoride ingestion during tooth development, resulting in tooth discoloration ranging from white streaks to brown stains and cracks or pits in the tooth enamel. "It would be interesting to probe the potential role of AMTN in ion transport by comparing the distribution of fluoride that is supplied in the drinking water in wild type and AMTN-deficient mice in light of dental fluorosis as a clinical problem." (PMID 25309457, 2014).
esophageal cancer (1 paper, 2023). A primary or metastatic malignant neoplasm involving the esophagus. "constructed a prognostic map for esophageal cancer, utilizing eight genes, including CDCA4, UBE2Z, AMTN, AK1, TLE1, FXN, ZBTB6, and APLN." (PMID 38098487, 2023).
geographic atrophy (1 paper, 2024). "Changes in the expression profile of the extracellular matrix led to the discovery that amelotin is induced in AMD and is associated with the development of the calcium deposits seen in late-stage geographic atrophy." (PMID 39325754, 2024). "We have also identified a gene, AMTN, that may play a critical role in the pathology of geographic atrophy." (PMID 39325754, 2024).
AMTN also shares sentences with these, for which no sentence is quoted: amelogenesis imperfecta (3 papers); chronic periodontitis (1); genetic diseases (1).